RPGRIP1 (RPGR interacting protein 1)
Diseases named in the same sentence as RPGRIP1 in open-access papers (continued):
Sharing a sentence is not in itself a finding about the gene and the disease.
retinal diseases (7 papers, 2007 to 2025). "RPGRIP1 interacts with other retinal disease-causing proteins and has been proposed to have a role in ciliary protein transport; however, its function remains elusive." (PMID 29203866, 2017). "Mutations in RPGRIP1 are a significant cause of inherited retinal diseases." (PMID 40737315, 2025). "The retinitis pigmentosa GTPase regulator interacting protein 1 (RPGRIP1) is a structural protein localized to the photoreceptor cilium and biallelic RPGRIP1 variants have been associated with non-syndromic human inherited retinal diseases." (PMID 37650070, 2023). "The CNGA3, CACNA1F, and RPGRIP1 genes are the most well-known from our list, and this article discusses their photoreceptor function and implications in retinal diseases." (PMID 40737315, 2025). "The ciliary protein interactome appeared abnormal in all RGPRIP1 variant organoids and was sufficient to perturb the transport of rhodopsin and L/M-opsin to the OS of photoreceptors, a phenotype that has been described in RPGRIP1 null murine models and other retinal disease organoid models." (PMID 41270749, 2025). "A recent WES analysis of 1210 Japanese pedigree patients with inherited retinal diseases revealed no pathogenic variants of RPGRIP1." (PMID 37761981, 2023). "These individuals were selected through gene-panel molecular diagnostics of a cohort of 722 probands addressed for a retinal disease suggestive of LCA, which identified biallelic and monoallelic unequivocal RPGRIP1 pathologic variants in 26/722 and 6/722 individuals, respectively." (PMID 33670832, 2021). "In this study, RPGRIP1, RANBP2, NPM1, PDE6D, NPHP5, and ABCA4 genes were selected on the basis of interaction with RPGR or RPGRIP1 or their implication in related retinal diseases, and were investigated as candidate genetic modifiers of XLPRA1." (PMID 17653054, 2007).
glaucoma (5 papers, 2011 to 2022). Increased pressure in the eyeball due to obstruction of the outflow of aqueous humor. "Moreover, it has been suggested that RPGRIP1 is directly implicated in various forms of glaucoma, including POAG." (PMID 32545285, 2020). "Fernandez-Martinez L showed that the RPGRIP1 gene, which was known as retinitis pigmentosa GTPase regulator-interacting protein 1, was considered as a risk factor for primary open angle glaucoma, and that variants of RPGRIP1 might increase an individual’s susceptibility to various forms of glaucoma." (PMID 34399712, 2021).
hyperopia (5 papers, 2013 to 2024). A refractive error in which rays of light entering the eye parallel to the optic axis are brought to a focus behind the retina, as a result of the eyeball being too short from front to back. "However, in our cohort, all four patients with RPE65 variants had hyperopia, and in contrast, two of 14 patients with RPGRIP1 variants had myopia." (PMID 38662103, 2024). "Notably, the individual displayed unilateral myopia and night blindness, in contrast to the moderate hyperopia and photoaversion typically associated with RPGRIP1 mutations." (PMID 38892339, 2024). "In LCA type I patients originating from this region with moderate or no hyperopia, RD3 should be screened for mutations first, before GUCY2D, RPGRIP1 and CEP290." (PMID 23308101, 2013). "Refraction may represent a distinctive feature in LCA type I since patients with GUCY2D mutations consistently have high hypermetropia (>+7) with frequent enophthalmia whereas those who harbor RPGRIP1, CEP290 or RD3 mutations present with lower or no hyperopia (, present study)." (PMID 23308101, 2013).
myopia (4 papers, 2017 to 2024). "Thus, we hypothesize that, like patients with RPGR mutation, patients with RPGRIP1 may be more prone to developing myopia." (PMID 38662103, 2024). "An individual with RPGRIP1 mutations reported hypermetropia and one TULP1‐affected individual reported myopia." (PMID 29178642, 2017). "In the four patients reported with high myopia, the exact refractive error was not specified, but interestingly, they all shared the same unique homozygous mutation, c.2889delT (p.Ser964fs), that did not appear in any other RPGRIP1 patients." (PMID 34722527, 2021).
night blindness (3 papers, 2010 to 2024). Inability to see clearly in dim light. "Symptoms of night blindness were reported by 11 individuals, including CRB1 or TULP1 mutations (all individuals; three each group), RPGRIP1 or RPE65 mutations (two individuals each) and RDH12 mutations (one individual)." (PMID 29178642, 2017).
Photophobia (3 papers, 2008 to 2021). Excessive sensitivity to light with the sensation of discomfort or pain in the eyes due to exposure to bright light. "RPGRIP1 variants were also identified in patient 22–50 (Family 22)—the 40-year-old woman with a reduction of visual acuity to the level of counting fingers, photophobia, and hyperopic astigmatism." (PMID 33308271, 2020). "Case 13, who had novel mutations in RPGRIP1, had a history of photophobia and displayed peripheral hyperpigmentation in the retina." (PMID 18682808, 2008).
achromatopsia (2 papers, 2017 to 2025). Achromatopsia (ACHM) is a rare autosomal recessive retinal disorder characterized by color blindness, nystagmus, photophobia, and severely reduced visual acuity due to the absence or impairment of cone function. "Interestingly, we found that one of the control samples also carried additional pathogenic variants in ABCA4 gene and RPGRIP1 gene and this sample was from a patient who was diagnosed with Achromatopsia (RD13–08)." (PMID 28838317, 2017).
retinal ciliopathy (2 papers, 2024 to 2025). "In canine models of naturally occurring retinal ciliopathy, homozygous variants in genes such as NPHP4, NPHP5, and RPGRIP1 have been identified as causes of CRD,51–53 despite these genes being similarly expressed in both rods and cones." (PMID 39898911, 2025). "In canine models of naturally-occurring retinal ciliopathy, homozygous variants in genes such as NPHP4, NPHP5, and RPGRIP1 have been identified as causes of CRD, despite these genes being similarly expressed in both rods and cones." (PMID 38979372, 2024).
autosomal recessive cone-rod dystrophies (1 paper, 2008). "Seven genes reported to be associated with autosomal recessive cone-rod dystrophies (crd), ABCA4, RDH5, CORD8, CORD9, RPGRIP1, CRX and GUCY2D were therefore included in the study." (PMID 18593457, 2008).
breast carcinoma (1 paper, 2013). "In breast cancer development there is little information on cilia involvement available, however, the cilia-associated genes Gli1 (Hh effector), RPGRIP1 (LCA) and DNAH9 (PCD) are commonly mutated in breast cancer." (PMID 23628112, 2013).
developmental delay (1 paper, 2021). "It is possible that developmental delay or intellectual disability in patients with RPGRIP1 mutations is caused by the same molecular pathway." (PMID 34722527, 2021). "RPGRIP1L and RPGRIP1 are known to interact with the NPHP4 C2 domain, and mutations in both can cause developmental delay by interfering with neuronal development." (PMID 34722527, 2021). "Intellectual disability or developmental delay was reported in 12 patients with RPGRIP1 disease." (PMID 34722527, 2021).
epilepsy (1 paper, 2018). A brain disorder characterized by episodes of abnormally increased neuronal discharge resulting in transient episodes of sensory or motor neurological dysfunction, or psychic dysfunction.
keratoconus (1 paper, 2013). A degenerative, structural disorder of the eye, characterized by a cone-shaped protrusion of the cornea. "In one patient (LCA81–1) identified with nonsense RPGRIP1 mutation, the clinical diagnosis indicated a cornea plana (lesser K readings suggesting a flater cornea) in contrast to keratoconus, an associated clinical feature of LCA described usually with AIPL1 and CRB1 mutations." (PMID 24066033, 2013).
macular degeneration (1 paper, 2007). Loss of vision in the central portion of the retina (macula), secondary to retinal degeneration. "RPGRIP, RANBP2, NPM1, PDE6D, and NPHP5 were selected on the basis of protein interaction with RPGR or RPGRIP1 as these two proteins independently cause photoreceptor degeneration when mutated; ABCA4 was selected as a control gene, and because of its association with macular degeneration and RP." (PMID 17653054, 2007).
macular edema (1 paper, 2021). "Interestingly, none of our patients showed cystoid changes or macular edema, and CME was also not reported among RPGRIP1 patients in the literature." (PMID 34722527, 2021).
pigmented paravenous retinochoroidal atrophy (1 paper, 2023). "RPGRIP1 variants have been reported to cause IRD, including retinitis pigmentosa (RP; #268000), cone–rod dystrophy (CRD; #120970), LCA, and pigmented paravenous retinochoroidal atrophy (PPRCA), and genetic and clinical data have been accumulated." (PMID 37761981, 2023).
polycystic kidneys (1 paper, 2018). "Furthermore, while Rpgrip1nmf247/nmf247 and Rpgrip1l+/− mouse embryos do not show any defects, their combined mutations induce polycystic kidneys in Rpgrip1l+/−; Rpgrip1nmf247/nmf247 embryos demonstrating a functional synergy of Rpgrip1l and Rpgrip1 in renal development." (PMID 29650680, 2018).
retinal tumor (1 paper, 2023). "To validate the localization of MAP9 and RPGRIP1 in primary cilia, we performed ICC with a cell culture model using mouse-derived immortalized retinal tumor cell line, 661W." (PMID 37650070, 2023).
Visual impairment (1 paper, 2024). "Rodent (Crb1, Lrat, Mertk, Rpe65, and Rpgrip1), avian (Gucy2D), and canine (Rpe65) models for LCA and profound visual impairment have been successfully corrected employing adeno-associated virus or lentivirus-based gene therapy." (PMID 39055259, 2024).
retinal disorder (4 papers, 2009 to 2025). Any disease or disorder of the retina. "The variation in clinical signs and time for initial symptoms is especially true for retinopathies caused by the RPGRIP1 mutation, on a variable genetic background, such as is the case in the human population." (PMID 22550515, 2012). "The animal model based gene therapy trials for other LCA genes like LCA1 (GUCY2D), LCA4 (AIPL1) and LCA6 (RPGRIP1) are also in progress, which further provides a prospect for the effective treatment regime in inherited blinding retinal disorders." (PMID 24066033, 2013). "The RPGRIP1 protein was initially identified through the interaction with RPGR, which is responsible for an X-linked retinopathy in humans as well as X-linked PRA in Samoyed and Siberian Husky dogs." (PMID 19936303, 2009). "None of these genes, apart from RPGRIP1, has been implicated in retinopathies in humans, dogs, or mice." (PMID 19936303, 2009).
bacterial infection (1 paper, 2022). "Based on their average logistic regression coefficients, the five most important genes for bacterial classification were CEPT (+), RPGRIP1 (-), FCER1A (-), IFI27 (-), and PDE9A (-), where plus indicates upregulation and minus indicates downregulation for bacterial infection." (PMID 35184750, 2022).
cancer (1 paper, 2020). A tumor composed of atypical neoplastic, often pleomorphic cells that invade other tissues. "The top mutated genes identified in the EGFRvIII-PB tumors were Obscn, Hspg2, Rrbp1, Rpgrip1, and Atp5o which have unknown functions in cancer." (PMID 32727536, 2020).
RPGRIP1 also shares sentences with these, for which no sentence is quoted: Joubert syndrome (4 papers); Meckel syndrome (4); retinitis pigmentosa (4); congenital stationary night blindness (3); Blindness (2); Astigmatism (1); autosomal recessive retinitis pigmentosa (1); bradyopsia (1); COACH syndrome 3 (1); cone dystrophy (1); cone-rod dystrophy 13 (1); congenital nystagmus (1); corneal dystrophy (1); degenerative diseases (1); glomerulonephritis (1); infertile (1); Intellectual disability (1); iris hypoplasia (1); Joubert syndrome 7 (1); juvenile retinitis pigmentosa (1); Kidney Cyst (1); Leber congenital amaurosis 6 (1); Leber hereditary optic neuropathy (1); Macular dystrophy (1); nephronophthisis (1); Pigmentary retinopathy (1); primary open angle glaucoma (1); retinal (1); scoliosis (1); Sepsis (1).
A further 4 diseases each share a sentence with RPGRIP1 in 1 paper.